ACSS2 (acyl-CoA synthetase short chain family member 2)
Diseases named in the same sentence as ACSS2 in open-access papers (continued):
Sharing a sentence is not in itself a finding about the gene and the disease.
glioblastoma (16 papers, 2016 to 2025). The most malignant astrocytic tumor (WHO grade IV). "Previous studies indicates that ACSS2 is implicated in numerous biological processes, including lipid metabolism, oxidative phosphorylation, and histone acetylation, and is significantly associated with development and prognosis of various cancers such as glioblastoma and liver cancer." (PMID 38887280, 2024). "Glioblastoma tumors also consume acetate to generate acetyl‐CoA through ACSS2 enzymatic activity for energetic and lipid production purposes." (PMID 38105543, 2025). "Studies have shown that ACSS2 is overexpressed in glioblastoma, with a considerably higher concentration than in grade II and III gliomas." (PMID 40097417, 2025). "In a related publication, ACSS2 was found to be upregulated in glioblastoma compared to lower-grade lesions." (PMID 39915301, 2025). "OGT can activate ACSS2 following Ser-267 phosphorylation, and the regulation of glioblastoma cell growth in vivo is partly dependent on this phosphorylation." (PMID 40097417, 2025). "Phosphorylation of ACSS2 at S659 induces this translocation, where ACSS2 forms complexes with TFEB in the nuclei of glioblastoma cells." (PMID 40097417, 2025). "Our results are consistent with studies in glioblastoma where ACSS2 plays a key role in converting acetate to acetyl-CoA and lipids." (PMID 38818373, 2024). "Specifically, the upregulation of ACSS2 Ser-267 has been shown to facilitate the growth of glioblastomas through O-GlcNAc transferase activation." (PMID 38887280, 2024). "The expression level of ACSS2 in glioblastoma is correlated with tumor grade, and the more ACSS2 that is expressed in cells, the higher the tumor grade." (PMID 35740562, 2022). "Of interest, acetyl-CoA can be produced by PDH from glucose and by acyl-coenzyme A synthetase short-chain family member 2 (ACSS2) from acetate, both of which are closely associated with the biology of the malignant brain tumor, glioblastoma (GBM), through acetylation of cytosolic proteins." (PMID 33916219, 2021). "Acetyl-CoA generated by ACSS2 is also necessary to fuel breast tumour xenografts, as well as brain metastasis and glioblastoma growth in in vivo models." (PMID 29739810, 2018). "Notably, ACSS2 plays a pivotal role in glioblastoma development following its nuclear translocation." (PMID 40097417, 2025). "In particular, ACSS2 may serve as an attractive therapeutic target for tumors in the brain, such as glioblastoma and brain metastasic tumors, due to the preferential use of acetate in these tumors." (PMID 38818373, 2024). "ACSS2 is highly expressed in numerous tumours and several studies have shown that genetic depletion or pharmacological targeting of ACSS2 inhibits tumour growth in breast, prostate, liver, pancreatic, ovarian and skin cancers and glioblastoma." (PMID 35887244, 2022). "ACSS2-derived acetate is also essential for energetic purposes because numerous primary and metastatic brain tumours can rely on acetate oxidation for energy, as recently demonstrated in orthotopic models of both human glioblastoma and brain metastasis." (PMID 29739810, 2018). "Of note, our data are confirmed by independent studies showing lower activity of HK, SDH and ACSS2 and higher activity of CS in LGG compared to glioblastoma." (PMID 28467784, 2017). "Interestingly, the O-GlcNAcase inhibitor promoted ACSS2 Ser-267 phosphorylation in glioblastoma cells, without affecting normal astrocytes, highlighting its potential for further application in glioblastoma therapy." (PMID 40097417, 2025). "The function of ACSS2 is heavily influenced by OGT and O-GlcNAc, which are highly expressed in glioblastoma (GBM) cells." (PMID 37838167, 2023).
Obesity (12 papers, 2009 to 2024). Accumulation of substantial excess body fat. "It has been shown that ACSS2 deficiency reduces fat deposition and obesity caused by a high-fat diet, but is less able to stress during fasting." (PMID 35740562, 2022). "To further investigate adipose-specific ACSS2 function, we generated adipose-specific ACSS2 over-expression mice (AAV-ACSS2) to evaluate its phenotype with the high fat diet (HFD)-induced obesity by injected the AAV9 vectors encoding adiponectin-drived ACSS2 over-expression in wild type mice." (PMID 38332049, 2024). "D-mannose functions as a rapid ACSS2 inducer to resist obesity, improve glucose utilization and insulin resistance, and liver steatosis." (PMID 38332049, 2024). "Collectively, D-mannose can rapidly target adipose tissues to enhance ACSS2 to protect against obesity and improve its related insulin resistance and liver steatosis." (PMID 38332049, 2024). "In this respect, D-mannose is obviously different from glucose and initiates a complex of ACSS2 and PPARγ to target Ucp1 transcription, thereby improving obesity and its related disorders, such as glucose utilization, insulin sensitivity and liver steatosis." (PMID 38332049, 2024). "We thus reveal a novel ACSS2 function in coupling PPARγ activation with degradation via SIRT1 and suggest D-mannose as a novel adipose plasticity regulator via ACSS2 to prevent obesity." (PMID 38332049, 2024). "For example, ACSS2 contributes to obesity induced myeloma and patients with high levels of ACSS2 expression in myeloma cells have shorter overall survival than patients with low expression." (PMID 39086974, 2022). "QTLs related to complex obesity-related traits such as body weight, glucose and leptin levels were found to overlap within the Acss2 genomic region." (PMID 27483348, 2016). "In order to link the monocyte transcriptome to the obesity phenotypes observed in CAF-diet-fed rats, we investigated the association between the expression levels of Acss2 in peripheral monocytes and metabolism-related traits." (PMID 27483348, 2016). "Interestingly, D-mannose rapidly activates ACSS2-PPARγ-UCP1 axis to resist high fat diet induced obesity in mice." (PMID 38332049, 2024). "To investigate whether D-mannose anti-obesity like effect is depended on adipose ACSS2, we injected the AAV9 vectors encoding adiponectin-drived small RNA against Acss2 to down-regulate adipose ACSS2 expression in D-mannose-administrated HFD-treated mice." (PMID 38332049, 2024). "The findings demonstrated a key impact for obesity-induced ACSS2 on myeloma progression and could be important for other obesity-related malignancies." (PMID 37361580, 2023). "In multiple myeloma, adipocyte-secreted Angiotensin II (ANG-II) directly stimulates acetyl-CoA synthetase 2 (ACSS2) in myeloma cells, contributing to obesity-induced myelomatous tumorigenesis, and the inhibition of the ANG-II-ACSS2 axis prevents obesity-induced tumour growth." (PMID 37238992, 2023). "In obese MM patients, the expression of ACSS2 was significantly higher than healthy individuals, and the increased ACSS2 level was positively correlated with high BMI values, thus strengthening the link between obesity and MM." (PMID 37639069, 2023). "However, ACSS2 has been also evidenced to support tumor growth and may be an important linker in obesity-related myeloma." (PMID 38332049, 2024). "In addition to D-mannose clinical application in treating cancer, urinary infections, type 1 diabetes and diabetic wounds, we also support the possibility of putting forth D-mannose as a potential therapeutic strategy of obesity and its related disorders via ACSS2." (PMID 38332049, 2024). "Taken together, adipose-specific ACSS2 overexpression can enhance the BAT and ingWAT plasticity to protect against obesity and improve its related insulin resistance and liver abnormal lipid accumulation." (PMID 38332049, 2024). "In addition, ACSS2 may be an important linker in obesity-related myeloma." (PMID 36118359, 2022).
Obesity (continued). "Besides, adipose-specific ACSS2 over-expression improved levels of serum triglyceride (TG) and total cholesterol (T-CHO), obesity-related insulin resistance, glucose tolerance." (PMID 38332049, 2024). "Altogether, these experimental observations suggest that S263 phosphorylation of ACSS2 plays a crucial role in maintaining triglyceride level and in modulating insulin-induced AKT phosphorylation during obesity, thus highlighting it as a potential target in regulating glucose and lipid homeostasis." (PMID 27180971, 2016). "At these respects, ACSS2 may be an ideal target of anti-obesity without other side effects." (PMID 38332049, 2024).
myeloma (11 papers, 2022 to 2024). "Target gene transcription promoted tumorigenesis, and inhibition of the angiotensin II/ACSS2 axis inhibited the progression of obesity-associated myeloma." (PMID 35798917, 2022). "As the use of an ACSS2 inhibitor reduced myeloma growth both in vitro and in a diet-induced obese mouse model, the critical role of ACSS2 in MM was verified." (PMID 36909335, 2023). "Acetyl-CoA synthetase 2 (ACSS2) is overexpressed in MM cells derived from obese patients and contributes to myeloma progression." (PMID 37361580, 2023). "The importance of ACSS2 overexpression in myeloma was confirmed by finding that an ACSS2 inhibitor reduced myeloma growth in vitro and in a diet-induced obese mouse model." (PMID 37361580, 2023). "ACSS2-mediated IRF4 acetylation results in the elevation of IRF4 protein level due to dysregulation of p62-mediated lysosomal degradation in myeloma." (PMID 38060103, 2023). "Treatment of adipocyte-secreted angiotensin II enhanced the expression of ACSS2 in myeloma cells, which promotes tumorigenesis by maintaining the stability of interferon regulatory factor 4 (IRF4), an oncogenic protein." (PMID 38060103, 2023). "Overexpression of ACSS2 can be identified in myeloma cells from obese patients and promotes myeloma progression." (PMID 35798917, 2022). "Adipocyte-derived angiotensin II stimulated ACSS2 expression in myeloma cells, while upregulated ACSS2 interacted with the oncoprotein interferon regulatory factor 4 (IRF4) to enhance the its stability and expression by mediating its acetylation." (PMID 35798917, 2022). "A recent study showed that ACSS2 contributes to myeloma progression in obese patients and an ACSS2 inhibitor can reduce the growth of myeloma in vitro and in diet induced obese mouse models." (PMID 39086974, 2022). "It has been shown that the expression of ACSS2 in myeloma-infiltrated plasmacytes is much higher than that in normal plasma cells, and that the knockdown of ACSS2 in myeloma with a high ACSS2 expression inhibits tumor cell proliferation and colony formation." (PMID 35740562, 2022). "The expression of ACSS2 in myeloma cells of patients with malignant subtypes was significantly higher than that of patients with subtypes of good prognosis." (PMID 39086974, 2022). "In particular, the expression of ACSS2 is significantly higher in obese myeloma patients." (PMID 38060103, 2023). "ACSS2 is also overexpressed in malignant plasma cells derived from patients with myeloma." (PMID 38060103, 2023). "Therefore, whether the application of ACSS2 inhibitors combined with other treatments for myeloma will improve the survival rate and reduce recurrence remains to be further studied." (PMID 35740562, 2022). "The ACSS2-IRF4 complex was found in myeloma using co-immunoprecipitation, and the knockdown of ACSS2 decreased the function of IRF4 and significantly inhibited the growth of myelomas." (PMID 35740562, 2022). "Inhibitors of ACSS2 can be used to accelerate its degradation and thus reduce the level of IRF4 and inhibit the growth of myelomas." (PMID 35740562, 2022). "All human AML cell lines studied displayed high sensitivity to the ACSS2i when cultured in glucose with no added acetate, indicating the importance of ACSS2 in metabolism, as previously observed in myeloma cells." (PMID 36052997, 2022).
glioma (10 papers, 2011 to 2025). A benign or malignant brain and spinal cord tumor that arises from glial cells (astrocytes, oligodendrocytes, ependymal cells). "This process relies on the activity of ACSS2, which converts acetate to acetyl-CoA and fuels the TCA cycle; notably, ACSS2 expression is associated with poor survival in patients with gliomas." (PMID 29739810, 2018). "In glioma cells activation of AMPK by glucose restriction has been shown to stimulate the phosphorylation of cytoplasmic ACSS2 on Ser659 resulting in the translocation of ACSS2 to the nucleus." (PMID 33917812, 2021). "We confirmed that ME2 promotes SREBP-1 maturation and nuclear localization and increases ACSS2 expression, indicating that ME2 upregulates de novo lipogenesis, probably via AMPK–SREBP-1–ACSS2, in glioma cells." (PMID 34381734, 2021). "In conclusion, ME2 promotes PMT of GBM cells, and ACSS2 has an important role in the ME2-induced de novo synthesis of fatty acids in glioma cells." (PMID 34381734, 2021). "Recent research identified ACSS2 as a protein involved in glioma tumorigenesis via maintaining nuclear acetyl-CoA levels and activating lysosomal and autophagosomal gene expression in low-oxygen and low-glucose conditions." (PMID 32812201, 2020). "In IDH1WT glioma, ACSS2 showed an elevated mRNA expression compared to IDH1MUT glioma, suggesting a higher contribution of acetate to the acetyl-CoA pool in IDH1WT glioma." (PMID 28467784, 2017). "Thus, clarifying the epigenetic involvement of ACLY-FABP7 and ACSS2 under different conditions is important for understanding glioma tumorigenesis." (PMID 32812201, 2020). "S659-phosphorylated ACSS2 translocates to the nucleus, leading to the binding to downstream genes and acetyl-CoA production, which induces histone acetylation and gene expression for glioma development." (PMID 31750240, 2019). "This resonates with the high frequency of IDH1MUT in LGG cohorts and clarifies the observed association of ACSS2 expression and LGG patient survival, potentially reflecting the differences in ACSS2 expression and patient survival between IDH1MUT and IDH1WT glioma." (PMID 28467784, 2017). "These and the increased ACSS2 expression after temozolomide or mTORI treatments in vitro correlate to other studies where inhibited glucose consumption triggered AMPK activation and autophagy related acetate consumption in glioma cells." (PMID 30574020, 2018). "As a consequence of the absence of SIRT1 in gliomas, ACSS2-dependent production of acetyl-CoA from acetate will be aborted." (PMID 21655185, 2011).
pancreatic cancer (10 papers, 2017 to 2025). "Acetyl coenzyme A synthase short chain family member 2 (Acss2) is an acetyl coenzyme A synthase that promotes lipid synthesis and epigenetic reprogramming, while in a tumor context, metabolic stress in the body induces Acss2 expression, which is associated with poor prognosis in pancreatic cancer." (PMID 39220755, 2024). "We find that ACSS2 is generally highly expressed and promotes the proliferation and invasiveness of pancreatic cancer." (PMID 40908872, 2025). "The observed effects of depletion of ACSS2 on acetate-mediated effects on pancreatic cancer survival were specific to acidic conditions in vitro." (PMID 38429478, 2024). "We identify a mechanism of ACLY-dependent acetate secretion by stellate cells that orchestrates metabolic and epigenetic reprogramming in pancreatic cancer cells in an ACSS2-dependent manner." (PMID 38429478, 2024). "ACSS2 promotes macropinocytosis and facilitates metabolic reprogramming of pancreatic cancer in pancreatic cancer." (PMID 37152291, 2023). "SREBP2 and ACSS2 are already documented as pro‐survival factors in the acidic microenvironment of pancreatic cancers." (PMID 34811795, 2022). "Under metabolic stress such as hypoxia and/or low-nutrition conditions, expression of ACSS2 is elevated and ACSS2 promotes acetate uptake for lipid synthesis and membrane phospholipids in several cancers including pancreatic cancer cells." (PMID 29295482, 2017). "Moreover, the proliferation and invasion status induced by ACSS2 can be partly reversed by BCAT1 in pancreatic cancer cells." (PMID 40908872, 2025). "ACSS2 has been shown to be essential for the epigenetic regulation of lipogenic gene expression under hypoxic stress to support tumor survival and growth, and ACSS2-mediated metabolic reprogramming provides additional nutrients for macropinocytosis in pancreatic cancer." (PMID 38515158, 2024). "In summary, we believe that targeting the ACSS2-PPARD-BCAT1 axis has certain clinical value and can provide a new therapeutic strategy for the comprehensive treatment of pancreatic cancer." (PMID 40908872, 2025).
bladder cancer (9 papers, 2018 to 2025). "Immunohistochemical (IHC) analysis of bladder tumors with different aggressiveness showed that the ACSS2 expression level was associated with the aggressiveness of bladder cancer." (PMID 35740562, 2022). "Glucose-derived acetate and ACSS2 are also factors involved in cisplatin resistance in bladder cancer." (PMID 41281744, 2025). "Targeting ACSS2 and other metabolic vulnerabilities represents a promising strategy for overcoming chemoresistance in bladder cancer 62-66." (PMID 41281744, 2025). "Studies have found that in patients receiving cisplatin chemotherapy and patients with complete remission of bladder cancer have lower levels of ACSS2, but patients with drug-resistant and progressive bladder cancer have higher levels of ACSS2 expression." (PMID 35740562, 2022). "Recently, altered lipid metabolism was found in bladder cancer, and ACSS2 expression was found to be higher in the tissues of patients with cisplatin-resistant bladder cancer." (PMID 35798917, 2022). "For instance, ACSS2 is found overexpressed in cisplatin-resistant bladder cancer cells, while inhibition of ACSS2 can decrease FA synthesis by over 60% and affect the palmitoylation of specific proteins that regulate cell migration and proliferation." (PMID 34803494, 2021). "ACSS2 is highly expressed in cisplatin-resistant tissues, and targeted inhibition of fatty acid synthesis was shown to inhibit bladder cancer cell resistance." (PMID 34250022, 2021). "Further studies showed that the inhibition of ACSS2 could reduce resistance to cisplatin in bladder cancer." (PMID 35740562, 2022). "In T24R drug-resistant bladder cancer cells, enzymes involved in acetic acid use (ACSS2) and fatty acid synthesis (ACC) and fatty acid synthesis precursors (acetyl-CoA) levels are increased, leading to higher yields of glucose-derived acetic acid and fatty acids." (PMID 34250022, 2021). "Given that a significant increase in the levels of ACSS2 has been found in a series of cancer types, such as melanoma, breast, ovarian, and lung cancers, we speculated that ACSS2 expression may also be correlated with bladder cancer." (PMID 29568353, 2018). "Further studies have shown that ACSS2 but not the established ACLY promotes tumor resistance to cisplatin by providing acetyl-CoA to cisplatin-resistant bladder cancer cells via glucose-derived endogenous acetate." (PMID 35798917, 2022). "In addition, several crucial lipogenic enzymes including acetyl-CoA synthetase 2 (ACSS2) and ACC were overexpressed in cisplatin-resistant bladder cancer cells and treatment with ACSS2 inhibitor or ACSS2 siRNA could abate the cisplatin resistance." (PMID 39247819, 2024).